CXorf49 (chromosome X open reading frame 49)
Synonyms: CXorf49B
Gene: Protein-coding gene on chromosome X (71,714,371 to 71,718,285, reverse strand). Ensembl gene ENSG00000215115.
Homologues: Orthologues: chimpanzee CXHXorf49B (98% identical), mouse Gm4779 (38% identical), rat Cxhxorf49 (37% identical), mouse 4933412E24Rik (36% identical), rat 4933412E24Rikl (34% identical), mouse 8030474K03Rik (33% identical), rat Cxhxorf49B (33% identical), rat Cxhxorf49l1 (31% identical), mouse Gm3858 (31% identical). Paralogues in human: CXorf49B (100% identical), CXorf49C (72% identical).
Diseases named in the same sentence as CXorf49 in open-access papers:
CXorf49 is named in the same sentence as 2 diseases in open-access papers, as found by Europe PMC text mining. Sharing a sentence is not in itself a finding about the gene and the disease.
CXorf49 shares sentences with these, for which no sentence is quoted: endothelial dysfunction (1 paper); lung adenocarcinoma (1).